PPARG (peroxisome proliferator activated receptor gamma)
Diseases named in the same sentence as PPARG in open-access papers (continued):
Sharing a sentence is not in itself a finding about the gene and the disease.
cerebral infarction (4 papers, 2010 to 2020). An ischemic condition of the brain, producing a persistent focal neurological deficit in the area of distribution of the cerebral arteries. "Another studies also proved that PPARγ mediated neuroprotection after cerebral infarction." (PMID 26016630, 2015). "On the other hand, cerebral infarction is rescued by overexpression of PPARγ." (PMID 20862376, 2010).
Chronic colitis (4 papers, 2013 to 2021). A chronic inflammatory disease of the large intestine (colon, cecum and rectum). "Adoptive transfer studies using T cell-specific PPARγ null naïve T cells demonstrate that PPARγ is needed for suppressing effector responses at sites of inflammation such as the colonic LP in a mouse model of chronic colitis." (PMID 23592971, 2013).
diabetic neuropathy (4 papers, 2023 to 2025). A chronic, pathological complication associated with diabetes mellitus, where nerve damages are incurred due to diabetic microvascular injury involving small blood vessels that supply these nerves, resulting in peripheral and/or autonomic nerve dysfunction. "Inhibitors of PPARG ameliorated phenotypes in mouse models of chemotherapy-induced and diabetic neuropathy due to its neuroprotective properties, but a direct link connecting PPARG to peripheral neuropathy is not evident." (PMID 40343270, 2025). "Magnolol showed a great result in improving diabetic neuropathy in mice by reducing mitochondrial dysfunction in DRG neurons via the PPARγ/MKP-7/JNK/SIRT1/LKB1/AMPK/PGC-1α pathway and reducing inflammation through signaling of PPARγ/NF-κB." (PMID 40149566, 2025). "Of note, adiponectin can influence insulin, glucagon, glucose metabolism, TGs and free-fatty acids concentrations, while PPARγ can change accordingly to medium chain ACCs, being involved in antioxidant activity as well as in peripheral nerve injury and diabetic neuropathy." (PMID 37817933, 2023).
dry eye (4 papers, 2010 to 2024). "The crucial role of PPARγ expression in the lacrimal and meibomian glands and dry eye has been explored in mouse models." (PMID 38993197, 2024). "Qualitative PCR revealed that rats with dry eyes had significantly decreased PPARγ expression compared to healthy rats." (PMID 38993197, 2024). "Existing studies have revealed that downregulation of PPARγ was strongly relevant to lacrimal gland dysfunction in dry eyes." (PMID 35990826, 2022). "Collectively, the present results indicate that PPARγ and adiponectin-mediated signaling contribute to age-related increases in tear production in mice and have potential as therapeutic targets for the treatment of dry eye in humans." (PMID 31596727, 2019). "More interestingly, selective modulation of PPARγ activity may be a potential therapeutic strategy for the treatment of dry eye syndrome and meibomian gland dysfunction." (PMID 20664693, 2010).
edema (4 papers, 2018 to 2023). An abnormal accumulation of fluid beneath the skin, or in one or more cavities of the body. "In a mouse model of ALI, it was found to stimulate ENaC-mediated AFC through the PPARγ/SGK1 signaling pathway to mitigate pulmonary edema." (PMID 31160894, 2019).
essential hypertension (4 papers, 2014 to 2021). Hypertension that presents without an identifiable cause. "Several studies have assessed the relationship between PPARγ gene polymorphism and primary hypertension." (PMID 30777927, 2019).
Friedreich ataxia (4 papers, 2016 to 2024). An inherited condition that affects the nervous system and causes movement problems. "The effect of PPARγ activation has also been studied in Friedreich’s ataxia, an autosomal recessive disorder caused by mutations of the protein frataxin." (PMID 27352979, 2016). "Multiple PPARγ agonists, including PGZ, are capable of increasing the expression of FXN in the models of Friedreich Ataxia, a neurological disorder caused by FXN deficiency." (PMID 39334695, 2024). "However, recently, a novel brain penetrant and orally bioavailable PPARG agonist named Leriglitazone (MIN-102) was successfully tested in cellular and animal models of Friedreich ataxia." (PMID 37576821, 2023).
gastric adenocarcinoma (4 papers, 2012 to 2024). "The interleukin-1B gene (IL-1B), interleukin-1 receptor antagonist gene (IL-1RN), and PPARγ Pro12Ala polymorphism act in HP-associated gastric adenocarcinoma." (PMID 38357448, 2024). "The results of our study of PPARγ protein expression in gastric adenocarcinoma and normal mucosa with intestinal metaplasia adjacent to cancer were consistent with Sato's results." (PMID 22936949, 2012). "Also, a study with 277 patients showed that the presence of the prostaglandin PGD2 reduces tumor expansion of gastric adenocarcinoma by inhibiting the peroxisome proliferator-activated receptor gamma (PPARγ) pathway." (PMID 34199169, 2021). "However, recent studies have reported that redistribution of PPARγ expression occurs in human gastric adenocarcinoma." (PMID 22936949, 2012).
glaucoma (4 papers, 2019 to 2026). Increased pressure in the eyeball due to obstruction of the outflow of aqueous humor. "Rosglitazone, which is a PPARγ agonist, suppresses TGF-β1 expression and prevents conjunctival fibrosis after glaucoma filtration surgery." (PMID 32707656, 2020).
hemorrhage (4 papers, 2013 to 2024). Loss of blood from the vascular compartment to the exterior or into nonvascular body space as a result of rupture or severance of the blood vessels. "Blockade of PPARγ activation abolishes the salutary effects of maraviroc in the liver following trauma-hemorrhage." (PMID 24205332, 2013). "The effects of these treatments were then examined with respect to hepatic injury as well as hepatic myeloperoxidase (MPO) activity, intercellular adhesion molecule-1 (ICAM-1), interleukin-6 (IL-6), and PPARγ levels following trauma-hemorrhage." (PMID 24205332, 2013). "Previous studies have also shown that activation of the PPARγ attenuates the overproduction of cytokines, adhesion molecules, and neutrophil accumulation after trauma-hemorrhage." (PMID 24205332, 2013). "The depressed PPARγ following trauma-hemorrhage was restored by administration of maraviroc after trauma-hemorrhage." (PMID 24205332, 2013). "In all, we propose that APN works as a potential therapeutic agent to ameliorate the inflammatory response following GMH by enhancing the M2 polarization of microglia via AdipoR1/APPL1/AMPK/PPARγ signaling pathway, ultimately attenuating inflammatory brain injury induced by hemorrhage." (PMID 35720361, 2022). "However, the increase in PPARγ by maraviroc after trauma-hemorrhage was abolished by co-administration of GW9662." (PMID 24205332, 2013). "Furthermore, administration of the PPARγ antagonist GW9662 prevented the maraviroc-mediated attenuation of hepatic PPARγ protein expression after trauma-hemorrhage." (PMID 24205332, 2013). "In this study, we hypothesized that maraviroc administration in male rats, after trauma-hemorrhage, decreases cytokine production and protects against hepatic injury through a PPARγ-dependent pathway." (PMID 24205332, 2013). "In present study, we sought to determine whether PPARγ-dependent pathways play an important role in maraviroc-mediated hepatoprotection following trauma-hemorrhage." (PMID 24205332, 2013). "Furthermore, previous studies have shown that an increase in PPARγ activity improves liver function following trauma-hemorrhage or ischemia injury." (PMID 24205332, 2013). "We hypothesized that the beneficial effects of maraviroc following trauma-hemorrhage are mediated via a PPARγ-related pathway." (PMID 24205332, 2013). "Furthermore, administration of the PPARγ antagonist GW9662 prevented the maraviroc-mediated attenuation of hepatic MPO activity after trauma-hemorrhage." (PMID 24205332, 2013). "Another interesting study found a reduction of peroxisome proliferator-activated receptor gamma (PPARγ) in the VPM and VPL nuclei, which was co-localized with increased microglial expression in mice subjected to intra-thalamic hemorrhage." (PMID 39199436, 2024). "From this study, maraviroc activated hepatic PPARγ and decreased hepatic ICAM-1 and IL-6 levels and neutrophil activity following trauma-hemorrhage." (PMID 24205332, 2013).
Hypopharyngeal Squamous Cell Carcinoma (4 papers, 2020 to 2024). "PPARG has been reported to promote chemosensitivity in hypopharyngeal squamous cell carcinoma (HSCC)." (PMID 37791141, 2023). "This study is aimed at studying if PPARG sensitizes hypopharyngeal squamous cell carcinoma (HSCC) in chemotherapeutic treatments and at dissecting possible mechanisms of observed effects." (PMID 32373170, 2020). "Our previous study showed that the upregulation of peroxisome proliferator-activated receptor gamma (PPARG) could promote chemosensitivity of hypopharyngeal squamous cell carcinoma (HSCC) in chemotherapeutic treatments." (PMID 34054937, 2021). "It has been demonstrated that PPARG may interact with the PTEN-PI3K/AKT pathway, contributing to its involvement in the chemotherapy treatment of hypopharyngeal squamous cell carcinoma (HSCC)." (PMID 38505269, 2024).
IgA nephropathy (4 papers, 2014 to 2025). "PPARγ activation represses Ang-II signaling in IgA nephropathy and attenuates Ang-II-induced inflammation in vascular smooth muscle cells." (PMID 25122005, 2014).
infectious colitis (4 papers, 2014 to 2025). A viral or bacterial infectious process affecting the large intestine. "Kundu’s study demonstrated that gavage with Salmonella typhimurium suppressed PPARγ expression in gut epithelial cells, inducing acute infectious colitis." (PMID 40863173, 2025). "Here we report that S. Typhimurium induces acute infectious colitis by inhibiting peroxisome proliferator-activated receptor gamma (PPARγ) expression in intestinal epithelial cells." (PMID 24465207, 2014). "Despite these observations, the role of PPARγ in S. Typhimurium-induced infectious colitis remains unknown." (PMID 24465207, 2014). "At this juncture, the observed dichotomy in PPARγ's role in infectious colitis was surprising." (PMID 24465207, 2014). "In this study, we explored whether S. Typhimurium regulates host PPARγ levels during infectious colitis and evaluated PPARγ's contributions to the etiology of the disease." (PMID 24465207, 2014). "In fact, without the use of the Citrobacter rodentium infectious colitis model, the deleterious effects of PPARγ agonists would have been overlooked." (PMID 35288651, 2022).
irritable bowel syndrome (4 papers, 2018 to 2022). Irritable bowel syndrome (IBS) is a chronic functional condition of the lower gastrointestinal (GI) tract characterized by abdominal pain or discomfort and disordered bowel habit (diarrhea, constipation, or fluctuation between the two). "The studies suggest important associations between dysbiosis of commensal microbes and dysregulation of PPARγ in irritable bowel syndrome." (PMID 30658440, 2019). "In irritable bowel syndrome patients who experience alternating constipation and diarrhea (i.e., mixed-type irritable bowel syndrome), expression of PPARγ in colonic mucosa decreases." (PMID 30658440, 2019). "Pioglitazone can inhibit visceral allodynia and increase colonic permeability, but the PPARγ antagonist GW9662 completely reverses the effect of pioglitazone, indicating that pioglitazone may be used for irritable bowel syndrome (IBS) treatment by activating PPARγ." (PMID 31336903, 2019).
kidney injury (4 papers, 2020 to 2025). Trauma to the kidney. "Our study elucidated a novel PRMT1/UBE2m/NEDD4/PPARγ signaling axis that drives renal lipid metabolic dysfunction in CaOx crystal-induced kidney injury." (PMID 40744915, 2025).
leiomyoma (4 papers, 2007 to 2023). A well-circumscribed benign smooth muscle neoplasm characterized by the presence of spindle cells with cigar-shaped nuclei, interlacing fascicles, and a whorled pattern. "Estrogen-induced guinea pig uterine fibroids are similar to the human fibroids, in that they also expressed increased levels of PPARγ, RXR-α and all-trans retinoic acid." (PMID 17407572, 2007). "Results observed from a study on the influence of curcumin on Eker rat-derived uterine leiomyoma cell lines suggested that the curcumin inhibitory effect on leiomyoma cell proliferation occurs through the activation of peroxisome proliferator-activated receptor-gamma (PPARγ)." (PMID 33504114, 2021). "The involvement of many proteins such as FN1, COL1A1, BMP7, CCND1, EZH2, HMGA2, AhR, and E2F1 shown in the protein–protein interaction networks are well known in leiomyoma pathogenesis; others, such as SOX2, REN, PPARG, ABCB1, and NR3C1 are novel and require further investigation." (PMID 36835153, 2023). "Among the several mechanisms proposed in attributing the ability of PPARγ ligand in inhibiting leiomyoma cell growth, Houston suggested that the inhibition was mediated by negative cross-talk between ER and PPAR signaling pathway where the activation of PPARγ inhibits ER-mediated gene expression." (PMID 35800452, 2022).
liver failure (4 papers, 2012 to 2025). A liver disease characterized by the liver losing or has lost all of its function. "Synthetic PPARγ agonists, which include rosiglitazone (Avandia), troglitazone (Rezulin, withdrawn by the FDA due to causing liver failure), and pioglitazone (Actos; Takeda Pharmaceutical Ltd.), have provided insight into the therapeutic potential of PPARγ." (PMID 22693486, 2012). "In that respect, the FDA-approved PPARγ agonist rosiglitazone was suggested as a potential candidate for the treatment of liver failure." (PMID 33593348, 2021).
lymphedema (4 papers, 2021 to 2025). Excess fluid collection in tissues, causing swelling. "A defining late feature of lymphedema is adipose expansion, termed lymphedema-associated adipose tissue, characterized by up-regulation of inflammatory cytokines and lipid-handling genes such as PPARγ and C/EBPα." (PMID 41282012, 2025). "Here, we report on our findings with use of rosiglitazone, a pro-adipogenic agent, which functions as an agonist of peroxisome proliferator–activated receptor gamma (PPARγ), for the reduction of fibrosis in secondary lymphedema." (PMID 38131378, 2023). "Next, we sought to reverse the fibrosis observed in secondary lymphedema through augmented PPARγ activity." (PMID 38131378, 2023). "As previously documented, experimentally induced lymphedema in mice was connected with increased protein levels of proadipogenic transcription factors PPARγ and C/EBPα8." (PMID 33854130, 2021). "In the animal model of secondary lymphedema, enhanced activity of PPARγ, which is the master regulator of adipogenesis and lipogenesis in adipocytes, has been detected in subcutaneous area." (PMID 33854130, 2021). "The presence of fibrosis led to our hypothesis that rosiglitazone, a PPARγ agonist that inhibits fibrosis, would reduce fibrosis in a mouse model of secondary lymphedema after hind limb lymphadenectomy." (PMID 38131378, 2023). "We also analysed the degree of differentiation at the mRNA expression levels of typical adipogenic markers (PPARγ, perilipin, FAS, DGAT2, ATGL) -but we could not find major differences between cells derived from lymphedema patients and control subjects." (PMID 33854130, 2021).
Miscarriage (4 papers, 2013 to 2021). A pregnancy that ends at a stage in which the fetus is incapable of surviving on its own, defined as the spontaneous loss of a fetus before the 22th week of pregnancy. "Because we identified a downregulation of PPARγ in the IVT of miscarriages and a missing PPARγ expression in macrophages of RM cases, we might speculate that PPARγ ligands (e.g., prostaglandins) are released to a higher extent under these pathological circumstances." (PMID 29949879, 2018). "Their number is significantly enhanced in the decidua of spontaneous miscarriages whereas in recurrent miscarriages maternal macrophages seem to express PPARγ only in very few cases." (PMID 29949879, 2018). "The aim of this study was to investigate the combined expression pattern and frequency of PPARγ under physiological circumstances and in spontaneous and recurrent miscarriages in the trophoblast and in maternal macrophages of the decidua." (PMID 29949879, 2018). "Human placental tissues of the first trimester (15 physiologic pregnancies, 15 spontaneous abortion and 16 recurrent miscarriage placentas) were analyzed for expression of the nuclear receptor PPARγ." (PMID 29949879, 2018). "PPARγ expression in the syncytiotrophoblast of miscarriages was increased in comparison to the control." (PMID 23690759, 2013). "We correlated the IRS score of the nuclear receptor LXR, PPARγ, and RXRα in all miscarriage patients and all control trophoblast." (PMID 23690759, 2013). "For nuclear receptor, RXRα and PPARγ we also found an upregulation in spontaneous miscarriage." (PMID 23690759, 2013). "Furthermore, other research indicated PPARγ decreased within the trophoblasts, and PPARγ is involved in M2 polarization in decidual macrophages in uRM, thus suggesting that downregulation of PPARγ modulated the microenvironment at the maternal–fetal interface in recurrent miscarriage." (PMID 34502044, 2021). "We found a downregulation of PPARγ in the IVT compartment in both spontaneous and recurrent miscarriage on protein as well as on mRNA-level." (PMID 29949879, 2018). "To conclude, our data show that LXR expression is decreased in miscarriage and this is attended by changes in correlation changes of LXR with its heterodimer partners RXRα and PPARγ, possibly as a result of oxidative stress or proinflammatory processes." (PMID 23690759, 2013). "Within this study we could show that PPARγ is downregulated in the intermediate villous trophoblast (IVT) in both spontaneous (SM) and recurrent miscarriage (RM) placentas." (PMID 29949879, 2018).
mood disorder (4 papers, 2020 to 2023). A cognitive disorder a disturbance in which the person's mood is hypothesized to be the main underlying feature. "Although to date few studies have addressed the role of PPARγ agonists as antidepressants, our data suggest their potential use to treat mood disorders." (PMID 33219735, 2020).
neutropenia (4 papers, 2019 to 2024). A decrease in the number of neutrophils found in the blood. "PPARγ upregulation has previously been linked to changes in neutrophil function in patients with glycogen storage disease type Ib, where circulating neutropenia and defective respiratory burst are described, alongside increased levels of HIF-1α." (PMID 30849228, 2019). "In this region, several candidate genes (GATA2, PPARG, RAF1 and SEC61A1) associated with functions such as quantity of leukocytes or neutropenia were identified." (PMID 33116177, 2020).
obstructive sleep apnea (4 papers, 2019 to 2024). "PPAR signaling and PPARG expression in visceral adipose tissue have previously been associated with obstructive sleep apnea." (PMID 30990817, 2019).
Peripheral Nerve Injuries (4 papers, 2021 to 2025). "Some similar findings were also observed in animal models of peripheral nerve injury in which the expression of PPARγ was elevated and may act to protect neurons from nerve injuries." (PMID 37304762, 2023).
psoriatic arthritis (4 papers, 2012 to 2020). Joint inflammation associated with psoriasis. "Polymorphisms of PPARG have been seen in a cohort of psoriatic arthritis." (PMID 22957057, 2012).
retinal disease (4 papers, 2017 to 2025). "Molecular implications of PPARγ in retinal diseases have been reported thoroughly in several communications over the last decade." (PMID 33291567, 2020).